GALT (galactose-1-phosphate uridylyltransferase)
Diseases named in the same sentence as GALT in open-access papers (continued):
Sharing a sentence is not in itself a finding about the gene and the disease.
galactosemia (continued). "Previously, mutational analysis of the exons and flanking intronic regions of the GALT gene in Filipino classic galactosemia patients revealed two novel variants, c.347T>C (p.Leu116Pro) and c.533T>G (p.Met178Arg), neither previously investigated functionally." (PMID 31392114, 2019). "Classic galactosemia results from a deficiency in the galactose‐1‐phosphate uridylyltransferase (GALT) enzyme, which is essential for galactose metabolism." (PMID 31497475, 2019). "Classic galactosemia is a rare inborn error of carbohydrate metabolism, caused by a severe deficiency of the enzyme galactose-1-phosphate uridylyltransferase (GALT)." (PMID 31029175, 2019). "In contrast, GALT deficiency (type I classical galactosemia) is potentially lethal and demonstrates long-term, organ-specific complications." (PMID 29921957, 2018). "Many mutations in the GALT gene responsible for classic galactosemia have been described to give rise to variants with conformational abnormalities." (PMID 30477550, 2018). "Classical Galactosaemia (CG) (OMIM #230400) is a rare inborn error of galactose metabolism caused by deficiency of the enzyme galactose-1-phosphate uridylyltransferase (GALT)." (PMID 30231941, 2018). "Classic galactosemia is a genetic disorder of galactose metabolism, caused by severe deficiency of galactose-1-phosphate uridylyltransferase (GALT) enzyme activity due to mutations of the GALT gene." (PMID 28913702, 2018). "Of the galactosaemias ‘classical galactosaemia’ (due to galactose-1-phosphate pagesuridyltransferase deficiency or GALT deficiency) is the most common and managed by dietary restriction of lactose and galactose." (PMID 30198059, 2018). "Classic galactosemia (CG) (OMIM #230400) is a rare metabolic disease caused by a severe deficiency of galactose-1-phosphate uridylyltransferase (GALT), the second enzyme of the main pathway for galactose metabolism." (PMID 30477550, 2018). "Heterozygotes for the Duarte allele present 75% of GALT activity, homozygotes present 50% activity, and compound heterozygotes for the Duarte allele and a classic galactosemia allele present 25% activity in RBC." (PMID 28281081, 2017). "Classic galactosemia is a rare inherited disorder of galactose metabolism caused by deficient activity of galactose-1-phosphate uridylyltransferase (GALT), the second enzyme of the Leloir pathway." (PMID 28281081, 2017). "Patients with classic galactosemia suffer from a profound deficiency of galactose-1-phosphate uridylyltransferase (GALT) due to mutations in the GALT gene, and affected newborns present with a severe toxicity syndrome upon exposure to galactose in milk." (PMID 28831125, 2017). "Classic galactosemia is a potentially lethal disease caused by the dysfunction of galactose 1-phosphate uridylyltransferase (GALT)." (PMID 27005423, 2016). "In patients with classic galactosaemia due to GALT deficiency, galactose 1-phosphate is accumulated and the production of UDP–galactose is reduced, impairing the incorporation of galactose to proteins and lipids." (PMID 27707936, 2016). "Classic galactosemia (CG) is a potentially lethal inborn error of metabolism that results from the profound loss of galactose-1-phosphate uridylyltransferase (GALT), the second enzyme in the Leloir pathway of galactose metabolism." (PMID 27562100, 2016). "Inherited mutations on the GALT gene results in autosomal recessive, classic galactosemia (or type I galactosemia; OMIM #230400)." (PMID 27005423, 2016). "Classic galactosemia (CG) results from profound loss of galactose-1-P uridylyltransferase (GALT, EC 2.7.7.12), the second enzyme in the highly conserved Leloir Pathway of galactose metabolism." (PMID 27562100, 2016). "Classic galactosemia is a human autosomal recessive disorder caused by mutations in the GALT gene (GAL7 in yeast), which encodes the enzyme galactose-1-phosphate uridyltransferase." (PMID 24077966, 2014).
galactosemia (continued). "Classical galactosemia (OMIM #230400) is an autosomal recessive inborn error of metabolism caused by a deficiency of the galactose-1-phosphate uridyltransferase (GALT, EC2.7.7.12) protein, which is encoded by the GALT gene." (PMID 25124065, 2014). "Classic galactosemia is a hereditary disease affecting 1:60,000 newborns and is caused by mutations in the GALT gene that encodes the enzyme galactose-1-phosphate uridyltransferase." (PMID 24077966, 2014). "For example, Africa has an estimated prevalence of 1:14,000, which is based on a population-based screen of cord blood samples for the p.Ser135Leu GALT mutation and accounts for > 90% of all classic galactosemia cases in this population." (PMID 25124065, 2014). "To date, more than 230 mutations responsible for galactosemia have been identified and updated in the GALT gene databases." (PMID 25124065, 2014). "Thirty-four Korean patients with GALT deficiency galactosemia were recruited and a total of 51 variant alleles were identified (75.0%, 51/68 alleles)." (PMID 25124065, 2014). "Classic galactosemia is a human autosomal recessive disorder caused by deleterious mutations in the GALT gene that encodes the enzyme galactose-1-phosphate uridyltransferase." (PMID 24077966, 2014). "Classic galactosemia (CG) results from complete or almost complete loss of galactose-1-phosphate uridyltransferase (GALT), the second enzyme in the Leloir pathway of galactose metabolism." (PMID 25326312, 2014). "Only 21 Korean patients with GALT-deficient galactosemia have been reported, which suggests a low prevalence." (PMID 25124065, 2014). "Recently, others have also proposed the use of chemical chaperones as drug candidates for classic galactosemia based on the protein structural instability caused by disease-associated mutations on the human GALT gene." (PMID 24077966, 2014). "This is the least well understood form of galactosemia, behind type I (galactose 1-phosphate uridylyltransferase deficiency) and type II (galactokinase deficiency)." (PMID 21703329, 2011). "Classic galactosemia is a representative disease of an accumulation of galactose-1-phosphate, by GALT deficiency, which is known to be the most common cause of galactosemia." (PMID 19309526, 2009). "Galactosaemia is an inborn error of metabolism that occurs due to deficiency of GALT, galactokinase and uridine diphosphogalactose 4-epimerase enzyme deficiency." (PMID 20640127, 2009). "Moreover, mutations in the human GALT gene are associated with a pathological condition termed galactosemia, whereas mutations in the human GALE gene result in another disease called epimerase deficiency galactosemia." (PMID 40230451, 2025). "It is one of the most prevalent GALT alleles associated with clinical variant galactosemia." (PMID 40352451, 2025). "The GALT p.Ser135Leu (c.404C>T) variant is strongly linked to clinical variant galactosemia." (PMID 40352451, 2025). "In addition to GALT and total galactose screening, NBS for galactosemia included testing for six common GALT variants." (PMID 40352451, 2025). "Variants in the GALT gene have a potential therapeutic significance for classical galactosemia." (PMID 38778342, 2024). "Galactosemia is an autosomal recessive disorder produced due to GALT deficiency." (PMID 38832201, 2024). "Referencing the Galactosemia Proteins Database 2.0, we utilized the results of predictive modeling to analyze the possible effects of known missense mutations on the structure and activity of GALT." (PMID 36788839, 2023). "GALT sequencing in the remaining individual confirmed Duarte‐variant galactosaemia (DG)." (PMID 36873086, 2023).
galactosemia (continued). "This may be linked to the presence of contradictions in the clinical classification data due to the existence of Duarte galactosemia, which differs from classical galactosemia in that patients with Duarte galactosemia have a partial GALT deficiency." (PMID 36768784, 2023). "Classical galactosemia (GC) and Duarte galactosemia (DG) are caused by mutations in GALT." (PMID 36901862, 2023). "There are over 300 GALT mutations that are confirmed to cause classic galactosemia, but dozens of other variants have been documented with unknown clinical significance." (PMID 36788839, 2023). "Importantly, we identified a novel GALT gene missense variant (p.A303D) with a potential structural damaging effect in a patient with the classic form of galactosemia." (PMID 38139222, 2023). "Classic galactosemia is an autosomal recessive inherited liver disorder of carbohydrate metabolism caused by deficient activity of galactose-1-phosphate uridylyltransferase (GALT)." (PMID 38139222, 2023). "Based on this finding, we performed a literature review of all GALT missense variants identified in homozygous and compound heterozygous galactosemia patients carrying the p.K285N pathogenic variant to explore their molecular effects on the clinical phenotype of the disease." (PMID 38139222, 2023). "However, the major target is GALT deficiency galactosemia, which is diagnosed by assessing blood galactose concentration and erythrocyte GALT enzyme activity and, for certain programs, by performing mutation screening." (PMID 36615667, 2022). "Galactosemia caused by GALT deficiency may be further classified into three phenotypes: classic galactosemia, clinical variant galactosemia, and biochemical variant galactosemia." (PMID 36615667, 2022). "Thus, several types of galactosemia can be distinguished: type I resulting from GALT deficiency, type II resulting from GALK deficiency, type III resulting from GALE deficiency, and type IV resulting from GALM deficiency, respectively." (PMID 36615667, 2022). "Galactosaemia caused by mutation of GALT or GALT deficiency could induce ovarian toxicity, and polymorphism of GALT with galactose consumption and metabolism may be associated with the development of BOTs and the risk of EOCs." (PMID 33921111, 2021). "Furthermore, the data with [1‐13C]‐galactose on carriers of GALT deficiency and patients with severe classic galactosemia due to GALT deficiency as well as patients with hypomorphic forms due to p.Ser135Leu variant are comparable to our previous reports." (PMID 33977035, 2021). "Classic galactosemia (OMIM #230400) is an autosomal recessive disorder caused by homozygous or compound heterozygous pathogenic variants in the galactose-1-phosphate uridylyltransferase gene (GALT; 606999) on chromosome 9p13." (PMID 34030713, 2021). "Classic galactosemia is a rare inherited disorder of galactose metabolism caused by severe deficiency of the second step in the main pathway for galactose catalyzed by galactose-1-phosphate uridylyltransferase (GALT)." (PMID 29671189, 2018). "In humans, defects in the genes encoding galactokinase, GALT or GALE cause galactosaemia." (PMID 27707936, 2016). "The ability of human UGP to convert galactose 1-phosphate into UDP–galactose may be important to alleviate galactose 1-phosphate accumulation in patients with classic galactosaemia due to GALT deficiency." (PMID 27707936, 2016). "Galactosemia is a metabolic disorder caused by mutations in the GALT gene." (PMID 26217714, 2015). "Notably, this side activity of hUGP is of relevance in individuals suffering from classic galactosemia, a potentially lethal disorder caused by genetic defects in the Gal-1-P uridylyltransferase (GALT)." (PMID 25860585, 2015).
galactosemia (continued). "Based on annotated databases, mutations in the GALT gene could cause Galactosemia with an autosomal recessive mode of inheritance, so c.1043A>G was the suspected pathogenic mutation for this case." (PMID 26274329, 2015). "This variation was detected in one patient who was a compound heterozygote for the Duarte variant (D/G galactosemia) with 6.2 μmol/h/g Hb of GALT activity, which supports the hypothesis that this variation may be pathogenic rather than benign." (PMID 25124065, 2014). "In our study, there were eight patients with the D/G GALT biochemical phenotype among 34 GALT-deficient galactosemia patients, and these patients had an enzyme activity of 5.9–15.8 μmol/h/g Hb (median 7.0 μmol/h/g Hb), corresponding to 21.5–57.5% of the mean control value." (PMID 25124065, 2014). "Overall, our literature review revealed that the GALT K285N missense pathogenic variant, which was identified in compound heterozygosity with the novel variant A303D in our index case, has been found in association with several other GALT missense variants in patients with galactosemia." (PMID 38139222, 2023). "The diagnosis of classical galactosemia, including a partial deficiency, is then confirmed by a laboratory test for galactosemia to detect a high concentration of erythrocyte galactose-1-phosphatase, urinary galactitol, and by the identification of bi-allelic pathogenic variants in the GALT gene." (PMID 36615667, 2022). "Accordingly, the results from the structural analyses of the GALT mutants herein characterized strongly suggest that GALT aggregation associated with protein misfolding might be a major pathogenic mechanism in classic galactosemia, setting the basis for future studies on in vivo GALT aggregation." (PMID 25614870, 2014). "Classic galactosemia, as defined in the Online Mendelian Inheritance in Man (OMIM) (230400), is an autosomal recessive disorder caused by a deficiency in galactose-1-phosphate uridylyltransferase (GALT, EC 2.7.7.12) activity." (PMID 41462863, 2025). "This drop in gal‐1P with increasing age is fully consistent with prior reports from both galactosemia patients and GALT‐null rats and likely reflects a combination of factors." (PMID 40656659, 2025). "Individuals with classic galactosemia exhibit severely reduced GALT activity, typically less than 1% in red blood cells." (PMID 40352451, 2025). "Because the donor was GALT+, successful engraftment not only treated the leukemia but also conferred normal GALT activity in RBCs (25.3 nmol/h/mg Hb, reference range > =24.5), prompting the question—Does this patient still have galactosemia?" (PMID 40656659, 2025). "It will be important to compare the metabolic and phenotypic outcomes of this patient with those of other galactosemia patients who have also experienced liver transplant to determine the true impact of GALT activity restricted to the liver." (PMID 40352451, 2025). "Type 1 galactosemia is due to variants of the galactose-1-phosphate uridylyltransferase (GALT) gene mapped on chromosome 9p13 and is the most frequent galactosemia form." (PMID 40687627, 2025). "In India, it is recommended to include screening programs for treatable disorders like CH, CAH, G6PD, galactosemia (GALT), biotinidase, CF, and hemoglobinopathy variations such as sickle cell disease in target populations." (PMID 38832201, 2024). "In humans, severe GalT impairment results in the potentially fatal condition known as classic galactosemia." (PMID 37376584, 2023). "For example, the classic galactosemia model (galt knockout) was used to assess the effectiveness of the GALT mRNA injection by quantification of GALT enzyme activity and metabolomics at 5 days post-injection." (PMID 37446400, 2023). "Genetic testing can be beneficial for the early detection of some syndromes to help with screening and management, e.g., galactosemia (GALT gene) is included in three of five panels." (PMID 36981008, 2023).
galactosemia (continued). "Classical galactosemia (CG, OMIM #230400) is an autosomal recessive disorder of galactose metabolism caused by bi-allelic variations in the GALT gene, leading to a galactose-1-phosphate uridyltransferase (GALT) enzyme activity of less than 1%." (PMID 36902816, 2023). "Moreover, to gain further insight into the genotype–phenotype correlation of GALT pathogenic variants, we carried out a literature review of the clinical and molecular features of all missense variants reported as homozygous and compound heterozygous with c.855G>T (p.K285N) in galactosemia patients." (PMID 38139222, 2023). "Genetic analysis of the galactosemia genes, namely, GALT, GALE, and GALK1, led to the identification of four novel and four rare variants of uncertain significance." (PMID 38090149, 2023). "The classic galactosemia mouse model showed that systemic administration of packaged GALT mRNA resulted in the expression of the enzyme in the liver." (PMID 37446400, 2023). "A previous study investigating the abundance and activity of GALT protein in galactosemia patients revealed that the p.R231H missense substitution is associated with a marked reduction in protein levels and close to null GALT activity." (PMID 38139222, 2023). "From a technical point of view, NBS for galactosemia can be performed by measuring total blood galactose (TGAL) or by GALT activity assay, both on a DBS using a fluorometric assay." (PMID 35883524, 2022). "The most common and severe type is called classic galactosemia characterized by a (very) low GALT activity." (PMID 35883524, 2022). "The GALT activity assay determines the enzymatic activity of GALT, the most commonly affected enzyme in galactosemia by semiquantitative spectrophotometric detection of NADH or NADPH." (PMID 35883524, 2022). "Efforts to reduce the number of false positives of the screening for classic galactosemia tend to use GALT activity as exclusive first tier, which precludes screening for GALE deficiency." (PMID 36056436, 2022). "Our group uses a GalT gene-trapped mouse model to study the pathophysiology of primary ovarian insufficiency in Classic Galactosemia." (PMID 36414970, 2022). "NBS for galactosemia is performed by assessing total galactose and/or GALT activity using a small amount of blood collected from the baby’s heel within 72 h of life." (PMID 35883524, 2022). "Deficits in three enzymes in this pathway, namely galactose-1-phosphate uridylyltransferase (GALT), galactokinase (GALK1), and UDP-galactose-4′-epimerase (GALE), are associated with genetic galactosemia." (PMID 34842598, 2021). "Novel therapeutic approaches for classic galactosemia currently (defined as: in the last 5 years) being explored aim either to (i) restore GALT activity, (ii) influence the cascade of events or (iii) address the clinical picture." (PMID 33525536, 2021). "The enzyme galactose-1-phosphate uridylyltransferase (GALT) in the Leloir pathway is less active among women and is the most common defect in the congenital condition galactosaemia." (PMID 32899514, 2020). "In the Wisconsin NBS program, galactose-1-phosphate uridylyltransferase (GALT) enzyme activity is the primary marker for galactosemia screening." (PMID 33124618, 2020). "Classical galactosaemia represents the most severe form of this disorder as a result of profound impairment in GALT resulting in accumulation of galactose, galactose-1-phosphate, galactitol, and galactonate in body tissues and fluid." (PMID 31652573, 2019).